PON1 (paraoxonase 1)
Diseases named in the same sentence as PON1 in open-access papers (continued):
Sharing a sentence is not in itself a finding about the gene and the disease.
liver disease (22 papers, 2009 to 2025). "Not much is known about the biochemical mechanisms underlying these alterations in PON1 synthesis and secretion in liver diseases." (PMID 20470383, 2010). "Abnormalities in the composition of lipids and proteins of HDL particles, including PON1 glycosylation, are associated with the decrease in serum PON1 activity in patients with liver disease." (PMID 20470383, 2010). "We conclude that abnormalities in the composition of lipids and proteins of HDL particles are associated with the decrease in serum PON1 activity in patients with liver disease." (PMID 20470383, 2010). "This becomes especially critical in conditions where systemic inflammation, with an expected decreased PON-1 activity (e.g., canine leishmaniasis, leptospirosis), may coexist with hepatic disease, possibly causing an increase (liver injury) or a further decrease (liver failure) in PON-1 activity." (PMID 39409835, 2024). "PON-1, which is an enzyme produced by the liver, demonstrates decreased activity in people with liver diseases, especially in patients with chronic disease manifestations, and it has been proposed as a biomarker for evaluating liver function in humans." (PMID 39409835, 2024). "The results obtained here suggest the importance of interpreting PON-1 activity cautiously in dogs with suspected liver disease." (PMID 39409835, 2024). "The interquartile range of this latter group showed how the data concerning PON-1 activity were widely distributed, suggesting the need for further subclassification based on suspected liver disease." (PMID 39409835, 2024). "The aim of this study is to investigate PON-1 activity variations among dogs suspected of liver injury or failure, evaluating the influence of hepatic diseases on PON-1 activity." (PMID 39409835, 2024). "It is the first reported study about site-specific PON1 glycosylation in AFP-negative liver disease conditions." (PMID 33889548, 2021). "Quantitative lens culinaris agglutin (LCA) ELISA was further used to confirm the difference of glycosylation on serum PON1 in liver diseases (n = 56)." (PMID 33889548, 2021). "This identified relationship postulates a role for DNA methylation as a mediator between PON1 genetics and expression, which is believed to further influence liver disease progression via modifications in PON1 catalytic efficiency." (PMID 34389043, 2021). "Previous authors have proposed two mechanisms to explain the decrease in activity in PON1 in liver disorder patients." (PMID 20339175, 2010). "Previous studies from our group showed that PON1 activity in patients with liver disease is inversely related to PON1 mass." (PMID 20470383, 2010). "The possibility exists that highly glycosylated PON1 is abnormally assembled into HDL particles in liver disease secondarily to alterations in protein synthesis in hepatocytes or to altered hepatic lipid metabolism." (PMID 20470383, 2010). "More recent evidence indicates that PON1 over-expression provides strong protection against the development of experimental liver disease." (PMID 19144177, 2009). "We have reported previously that serum PON1 activity is decreased in patients with liver diseases, while serum PON1 concentration and hepatic PON1 protein expression are increased." (PMID 19144177, 2009). "We suggest a hepato-protective role for PON1 against inflammation, fibrosis and liver disease mediated by MCP-1, and propose a hypothetical model to explain the hepatic PON1 alterations observed." (PMID 19144177, 2009). "Our results from this experimental model suggest a hepato-protective role for PON1 against inflammation, fibrosis and liver disease mediated by MCP-1." (PMID 19144177, 2009). "PON1 has been hypothesized to regulate hepatic parenchymal cell death, and hence its overexpression protects against the development of experimental liver disease." (PMID 38467965, 2025). "However, information regarding PON-1 activity and liver disease in the canine species is limited in the literature." (PMID 39409835, 2024).
liver disease (continued). "Given the hepatic synthesis of this enzyme, the presence of liver diseases may influence PON-1, thus affecting its reliability as a biomarker for inflammatory/oxidative systemic diseases." (PMID 39409835, 2024). "Considering that PON-1 is predominantly synthesized in the liver, it is reasonable to hypothesize that the presence of liver disease could impact the serum activity of this enzyme." (PMID 39409835, 2024). "The goal was to observe how PON-1 levels change in dogs with suspected liver diseases." (PMID 39409835, 2024). "Furthermore, several investigations have shown a significant reduction in PON1 activity among individuals afflicted by advanced liver disease compared to their healthy counterparts." (PMID 38136158, 2023). "We also reported that hepatic PON1 gene expression decreases in liver diseases." (PMID 38136158, 2023). "The patients with liver disease also exhibited higher serum PON1 concentration." (PMID 37908943, 2023). "One may posit that these increased PON1 mRNA and protein levels may reflect a compensatory production of PON1 after the onset of liver disease." (PMID 33923656, 2021). "As PON1 is mainly produced in the liver, PON1 may become an important and useful research target in liver diseases." (PMID 33923656, 2021). "However, another study reported that the production of PON1 was suppressed in liver disease, leading to low PON1 activity." (PMID 33923656, 2021). "Few studies have evaluated PON1 activities and the PON1 genotype in patients with liver disorders." (PMID 31847187, 2019). "Therefore, it is easily inferred that the significant decline of serum PON1 concentrations or activity can profoundly affect liver disease status." (PMID 26632904, 2015). "PON1 enzyme levels can range widely even between individuals with the same PON1 phenotype and PON1 phenotypes do not influence changes in PON1 associated with some clinical conditions such as hepatic disease." (PMID 24666514, 2014). "Taking these data together, we can hypothesize that abnormal PON1 molecules are synthesized under diverse altered conditions such as liver disease, or when human PON1 is synthesized by phylogenetically-distant cells." (PMID 20470383, 2010). "Additionally, the main site of PON-1 production is the liver and therefore decreased PON-1 synthesis may occur when liver disease or dysfunction is present." (PMID 41295705, 2025). "PON1 could serve as an indicator of the liver disorders in psoriasis." (PMID 35888704, 2022). "Paraoxonase 1 (PON1) is a widely studied enzyme based on its protective role against poisoning by organophosphate (OP) metabolites of specific OP insecticides and in vascular disease, as well as its use as biomarker of diseases involving oxidative stress, inflammation and liver diseases." (PMID 24666514, 2014). "We investigated the relationships between hepatic PON1 and MCP-1 expression in rats with liver disease and explored the possible molecular mechanisms involved." (PMID 19144177, 2009). "Liver diseases, including NAFLD, may lead to enhanced catabolism and/or the inactivation of PON1 molecules, which is a potential explanation for the low PON1 activity, as observed in the present meta-analysis." (PMID 33923656, 2021). "Most of these works showed PON1 activities to be decreased in patients with NAFLD/NASH, but, in many cases, the results were inconsistent, leaving many questions rather than clarifying the impact of PON1 in this liver disease." (PMID 31847187, 2019). "Also, the present study suggests that PON1, PON3, and PPAR-δ had protective roles against liver disease." (PMID 25478064, 2014).
dementia (21 papers, 2017 to 2025). Loss of intellectual abilities interfering with an individual's social and occupational functions. "Several human clinical studies have shown that low serum PON-1 activity leads to an increased risk for dementia and AD." (PMID 37108044, 2023). "These loci are associated with several dementia-related genes, including PON1, AP2A2, MAGI2, POT1, ITGAX, PACSIN1, SLC2A8, and EIF4E." (PMID 35299244, 2022). "In 304 patients with all types of dementia the PON1-108T allele occurred significantly more frequently in patients with AD than in controls, but the prevalence of Q192R genotypes was similar in both investigated groups." (PMID 33670025, 2021). "This is interesting because the 55MM genotype has been associated with lower PON-1 esterase activity, and several studies have associated lower PON-1 activity with an increased risk of both depression and dementia, and decreased cognition in elderly." (PMID 31052559, 2019). "In support of this notion are studies showing decreased serum/plasma PON-1 activity in neurological disorders associated with increased oxidative stress and/or neuroinflammation such as autism, multiple sclerosis, and dementia." (PMID 32963743, 2020). "The arylesterase activity of PON1 was significantly attenuated in patients with dementia, more so in patients with severe cognitive deficits." (PMID 39594433, 2024). "PON1 SNPs have also been investigated in the context of other dementias (e.g., AD), for which any connection with any SNP is very inconclusive." (PMID 36829958, 2023). "Relationships between PON1, lipid peroxidation, and dementia were examined in patients with AD (n = 63), vascular dementia (n = 40), and mixed dementia (n = 33)." (PMID 37175471, 2023). "The enzyme paraoxonase 1 (PON1) has previously been investigated as a potential biomarker in the context of other types of dementia." (PMID 36829958, 2023). "PON1 arylesterase activity was decreased in patients with dementia, more so in those with severe cognitive deficits." (PMID 37175471, 2023). "In the same year, another group demonstrated for the first time the presence of PON1 activity in human cerebrospinal fluid, with more recent articles reporting decreased cerebrospinal fluid PON1 activity in dementia and AD patients." (PMID 33668379, 2021). "Decreased PON-1 activity and decreased PON-2 expression were associated with nervous system oxidative stress and the development of dementias." (PMID 31052559, 2019). "In the present study, we did show a positive correlation of resistin with inflammatory indicators (interleukin-6 and CRP) and a negative correlation with anti-inflammatory markers (HDL-C and PON1 activity) in all dementia patients." (PMID 28421328, 2017). "We also tested whether there is any association between dementia status/MMSE on the one hand and PON1 kinetic parameters on the other hand for the reaction with DHC." (PMID 36829958, 2023). "Indeed, PON1 activity is lower in AD and dementia patients compared to healthy controls and correlates with the severity of AD-related cognitive decline." (PMID 37175471, 2023). "PON-1 mechanistic enzymatic activity needs to be further explored through basic science and human clinical studies; however, its activity can be inferred to be the main means of protecting the central nervous system against AD and other forms of dementia." (PMID 37108044, 2023). "Other proteins associated with HDLs that could be relevant to HDL metabolism and/or dementia include apolipoprotein C-I, paraoxonase 1 (PON1), and serpin family A member 1 (SERPINA1)." (PMID 30487733, 2018). "Furthermore, lower PON1 arylesterase activity has also been associated with mild cognitive impairment, suggesting that alterations in PON1 activity may be an early event in dementia progression." (PMID 38672443, 2024).
dementia (continued). "This ties back to one of our aims in the present study: to ascertain whether dementia status, which is the default measure of cognitive status in articles investigating the connection between PON1 and dementia, can also be usefully supplemented by recording the MMSE score." (PMID 36829958, 2023). "Highly significant positive correlation between the level of resistin and age and indices of inflammation (IL-6 and hsCRP, chitotriosidase activity) and a negative correlation with HDL-cholesterol and PON1 activity was stated in patients with all-cause dementia." (PMID 28421328, 2017). "Intriguingly, a decrease in PON1 was already observed in patients with the so-called Mild Cognitive Impairment (MCI), the prodromal phase of dementia." (PMID 39456469, 2024). "Although our results suggest that there is no clinically useful correlation between cognitive status and PON1 genetic and enzyme-kinetic parameters in the context of PD, this does not imply that PON1 does not play a role in other kinds of dementia." (PMID 36829958, 2023). "Several other types of dementia, however, have not yet been investigated in connection with PON1; notable among them is PDD." (PMID 36829958, 2023). "We tested the association between clinical parameters (MMSE and presence/absence of dementia) and genetic variability of PON1." (PMID 36829958, 2023).
depression (20 papers, 2009 to 2025). "In the controls, PON1 rs705381 was associated with compulsions, PON1 rs705379 with social anxiety, depression, anxiety, and aggression, PON1 rs854560 with obsessions, anxiety, and social phobia, and IL6R rs2228145 with aggression." (PMID 38275640, 2023). "In the controls, PON1 rs705381 was associated with compulsions, while rs705379 was associated with social phobia, aggression, anxiety, and depression and rs854560 with social phobia, obsessive symptoms, and anxiety." (PMID 38275640, 2023). "Similarly, the PON1 polymorphism has been associated with depression and anxiety in individuals who are sensitive to contact with chemicals of nontoxic concentrations." (PMID 34439504, 2021). "Concurrently, decreased apoA1 and PON1 levels in depression compromise HDL’s anti-inflammatory capacity, allowing IL-6-driven neuroinflammation to persist." (PMID 40511456, 2025). "Overall, HDL-C reduction in depression reflects a multifactorial pathology involving LCAT/apoA1/PON1 dysfunction, cortisol-driven lipid dysregulation, and pro-inflammatory HDL remodeling." (PMID 40511456, 2025). "Associations were also found with PON1 rs705379 GA + AA in healthy individuals, i.e., BSPS (p = 0.002), Zung depression (p = 0.001), Zung anxiety (p = 0.001), and BDHI scores (p = 0.047)." (PMID 38275640, 2023). "PON1 rs705379 GG was associated with BSPS (p = 0.001), Zung depression (p = 0.005), Zung anxiety (p = 0.002), and BDHI scores (p = 0.040) in healthy controls." (PMID 38275640, 2023). "PON-1 was studied in patients with anxiety disorders, bipolar disorders, major depressive disorders, obsessive compulsory disorders, a major depression, and schizophrenia." (PMID 37511134, 2023). "On the other hand, Ogłodek tested a large number of patients with MDD and PTSD (in total 460 patients, only 60 with PTSD alone) and concluded that depression became more severe at decreased PON-1 concentrations (also measured with an ELISA test)." (PMID 35743392, 2022). "Bortolasci and colleagues conducted two studies: the first to examine PON1 status (PON1 activity and functional PONQ192R polymorphism based on a 2-substrate assay) in patients with major depression and bipolar disorder with nicotine dependence." (PMID 35893041, 2022). "The influence of the paraoxonase 1 (PON1) polymorphisms, which affect the formation of ROS/RNS and the immuno-inflammatory characteristics of depression, has also been discussed." (PMID 34439504, 2021). "PON1 activity was decreased by smoking and was diagnosed by genotypic interaction (i.e., lower PON1 in major depression with the QQ genotype)." (PMID 33050072, 2020). "Typically, individuals with depression show reduced PON1 and HDL-C levels." (PMID 40511456, 2025). "There appears to be agreement that PON1 activity is altered in patients with depressive disorders." (PMID 35743392, 2022). "Thus, depression in T2DM may stem from metabolic dysfunctions/MetS alongside diminished PON1 and HDL-C levels." (PMID 40511456, 2025). "In addition, PON1 polymorphisms have been associated with the occurrence of depression, although this is not entirely clear." (PMID 38049858, 2023). "mRNA expression of the PON1, PON2 and PON3 genes was slightly higher in patients with depressive disorders than in the control group, however, this relationship was not statistically significant." (PMID 35743392, 2022). "The measured inflammatory (IL-18, IL-33, MIP) and oxidative parameters (PON-1, GSH-Rd, OxLDL, iNOS, HO-1) in all patient groups deviated from HC, with the most deviation being evidenced by the PTSD group with comorbid depression." (PMID 34072322, 2021). "Subsequently, APOD, PON1, BCHE, and IL6ST were reported to be related to depression, a finding consistent with our results." (PMID 33126421, 2020).
depression (continued). "A previous study examined the role of genetic polymorphisms in oxidative stress in Multiple Chemical Sensitivity (MCS), revealing that the AG genotype of paraoxonase 1 PON1 rs662 and the TT and CT genotypes of PON1 rs705379 are involved in anxiety and depression in MCS." (PMID 39731452, 2025). "The authors suggested that reduced plasma PON1 activity may be a trait marker of major depression and that PONQ192R gene–environment (smoking) interactions differentially predict depression and bipolar disorder odds." (PMID 35893041, 2022). "mRNA expression of PON1, PON2 and PON3 genes was slightly higher in patients with depressive disorders than in the control group, however this relationship was not statistically significant (PON1 p = 0.5895, PON2 p = 0.1342 and PON3 p = 0.2818)." (PMID 35743392, 2022). "In addition, plasma activity of Paraoxonase 1 (PON1), a potent antioxidant that protects against lipid peroxidation, is lower in patients with depression." (PMID 32971941, 2020). "However, in another work authors found, that major depression, but not bipolar disorder in adults, was accompanied by lower PON1 activity." (PMID 33050072, 2020).